CSF1 (colony stimulating factor 1)
Diseases named in the same sentence as CSF1 in open-access papers (continued):
Sharing a sentence is not in itself a finding about the gene and the disease.
tumor (continued). "Finally, PDGFA and CSF-1 were highly expressed in this cluster suggesting tissue-remodeling properties essential for wound healing, which combined with upregulated TXN93 improve their capacity to create an immunotolerant environment and promote tumor progression." (PMID 33602930, 2021). "Thus the enhanced macrophage chemotaxis, could also be attributable to normoxia mediated induction and release of CSF-1, rather than signals emanating from hypoxic tumor cells." (PMID 25051364, 2014). "While the role of hypoxia in regulation of CSF-1 expression has not been previously determined, we hypothesized that CSF-1 levels may be higher at the tumor margin where invading cells are exposed to an oxygen-rich environment compared to the hypoxic tumor core." (PMID 19696929, 2009). "Downregulation of CSF-1 in GBM cells by fibulin-3 inhibition did not lead to increased IGF-1 in the tumor, possibly preventing this tumor-salvage pathway." (PMID 40844085, 2025). "Gal-2 promotes macrophage M2-like polarization and proliferation through the activation of the colony-stimulating factor 1 (CSF1)/CSF1 receptor (CSF1R) axis, thereby enhancing tumor growth in vivo but not in vitro." (PMID 40134029, 2025). "The radiotherapy-induced secretion of cytokines from tumor cells, such as CSF1, CCL2, and MCP3, promotes macrophage recruitment and activation from the irradiated tumor microenvironment to the non-irradiated tumor site." (PMID 40835598, 2025). "TAMs originate from mononuclear precursors, and the effect of chemokines, such as CSF-1, CCL2, VEGF, and TGF-β, is required for monocytes to reach the tumor site in the colon." (PMID 36709284, 2023). "High variability was seen in isolated single cell clone (SCS) CTC CSF1 RNA expression in RNA SEQ and in real-time RT-PCR suggestive of clonal variation within individual patient portal blood tumor cell populations (data not shown)." (PMID 35316296, 2022). "Furthermore, the molecular mechanism of CSF1/CSF1R in OSA remains unclear; the positive correlation with the expression of CSF1R and CD4/CD68 is not clear that it must play the positive effect on prognosis, and it may also be as a cancer promoting factor that involved in tumor immune escape." (PMID 32850346, 2020). "Overcoming TAM-mediated resistance involves strategies targeting their recruitment (e.g., CCL2/CCR2 blockade), survival/differentiation (e.g., CSF-1/CSF-1R inhibition), function (e.g., blocking “do not eat me” signals like CD47), or attempting to repolarize them towards an anti-tumor M1-like state." (PMID 40458806, 2025). "However, other reports indicated that inhibition of the CSF-1/CSF-1R axis did not obliterate all macrophages but pushed the TAMs toward the M1-like phenotype triggering CD8+ T cell activation and inhibiting tumor progression." (PMID 36902456, 2023). "However, combined treatment with the two antibodies had no additive effect on MC38 tumor growth, suggesting that OLFML3 may act along the CSF1/CSF1-R axis." (PMID 34572851, 2021). "Moreover, the 60 s kINPen plasma treatment, which reduced absolute lesion and tumor sizes significantly, was the only treatment not showing a reduction in ACVR1B, ACVR2A, CSF1, EGF, EGFR, IL15, and IL6RA when compared to all other treatments in the high dose DBP group." (PMID 34667240, 2021). "Interestingly, a knockdown of CCL2/CSF1 in tumor-initiating cells blocked M2 macrophage recruitment and abolished tumorigenesis in an immune system-dependent manner, suggesting that YAP-activated tumor-initiating cells are eliminated without the protection of M2 macrophages." (PMID 31052239, 2019).
cancer (489 papers, 1998 to 2026). A tumor composed of atypical neoplastic, often pleomorphic cells that invade other tissues. "The PI3K‐Akt signaling pathway plays a key role in cell growth, survival, metabolism, and motility, and activation of its related genes (MYD88, IL7R, MYB, CSF1) has been implicated in the initiation and progression of several cancers." (PMID 41328768, 2025). "Cancer-associated fibroblasts secrete colony-stimulating factor 1 (CSF-1) to increase the ROS content in monocytes, which induces an M2-type differentiation of macrophages." (PMID 38302980, 2024). "Elevated levels of CSF1 in plasma have been associated with various diseases and conditions, including inflammation, cancer, and certain autoimmune disorders." (PMID 39380021, 2024). "In a CSF-1R-overexpressing MCF-7 cancer cell line, CSF-1 induced cell cycle arrest associated with increased p21 levels and the formation of p21/CDK complexes preventing cell cycle progression." (PMID 38254773, 2024). "Studies have shown that high expression of CSF-1 or CSF-1R is associated with poor prognosis in some malignant tumors, such as Hodgkin’s lymphoma and hepatocellular carcinoma." (PMID 39403370, 2024). "Various diseases, such as cancer, inflammation, and bone disease, are linked to and made worse by the macrophage populations that are stimulated by CSF-1." (PMID 38045696, 2023). "Such an active immune state of the TME defined by the CD8A to CSF-1 expression ratio is associated with a positive response to αPD-1/αPD-L1 therapies in patients with cancer." (PMID 35292516, 2022). "Alkylating agents (like cisplatin and carboplatin) inhibit DNA replication from causing cancer cell death, wherein such dying cancer cells express more CSF1, thereby attracting large numbers of CSF1R+ TAMs (M2-like)." (PMID 36497148, 2022). "CSF-1 or CSF-1R expression in the TME has been associated with poor prognosis in many types of cancer." (PMID 34209703, 2021). "Promising new splice variants with a potential link with cancer are CSF1, PLOD2, SLK, SPAG9 and TSC2." (PMID 33845831, 2021). "High expression of CSF‐1 has been found in breast, prostate, pancreatic, gastric, and many other types of cancers, and its level has been closely associated with TAMs density and poor prognosis." (PMID 33463063, 2021). "The pro-inflammatory protein osteopontin (OPN) produced by cancer cells has been implicated in cancer promotion and metastasis, through the stimulation of CSF1 signaling in TAMs." (PMID 33815418, 2021). "CRC and other cancer types show high levels of CSF‐1, a vital macrophage regulator that is linked to poor prognosis." (PMID 32735377, 2020). "In particular, depletion of macrophages using antibodies which target colony stimulating factor 1 (CSF1) leads to a compensatory activation of neutrophils, which is induced by cancer-associated fibroblasts." (PMID 31616430, 2019). "Accordingly, targeting TAMs via the CSF1/CSF1R or CX3CL1/CX3CR1 signaling pathway is an attractive therapy for cancers associated with increased numbers of TAMs (reviewed in refs.46,47)." (PMID 30237497, 2018). "A major lineage regulator for macrophages, colony-stimulating factor 1 (CSF-1), was shown to be associated with poorer prognosis in different cancer types." (PMID 26942464, 2016). "Cancer cells stimulate the invasion of macrophages by secreting colony stimulating factor-1 (CSF-1), which in turn causes the macrophages to stimulate invasion of the cancer cells by secreting epidermal growth factor (EGF)." (PMID 21307399, 2010). "Immune cells also play important roles in cancer progression; for example, tumour-associated macrophages induced by colony-stimulating factor 1 promote invasiveness of cancer cells." (PMID 18594526, 2008). "Angiogenesis in several cancer types is linked to increased M-CSF/CSF1 expression." (PMID 40727443, 2025).
cancer (continued). "CSF1 then binds to the CSF1 receptor on the membrane of MSCs, ultimately leading to the recruitment of tumor‐associated macrophages and myeloid‐derived suppressor cells, thereby promoting cancer cell invasion and metastasis." (PMID 39070181, 2024). "Notably, several genes that were previously reported to be associated with cancer development were changed in their expression after CSF-1 stimulation." (PMID 36555673, 2022). "Whether YAP1 activity in cancer-associated fibroblasts drives the production of CSF1 or other growth factors is an important open question." (PMID 35930670, 2022). "For example, overexpression of CSF1 in breast, prostate, pancreatic, hepatocellular and colorectal cancers, and IL-34 expression in hepatocellular carcinoma, lung and colorectal cancers are associated with disease progression and unfavorable prognosis." (PMID 34803925, 2021). "Finally, CSF-1 expression was associated with poor disease-free and cancer-specific survival, and univariate and multivariate proportional hazard analyses indicated that it was also an independent prognostic biomarker for patients with UTUC." (PMID 31565097, 2019). "Colony stimulating factor-1 (CSF-1) is associated with M2 activation of macrophages in cancer." (PMID 26174804, 2015). "Such resistance may be caused by the production of CSF-1 and IL-34 not only by aggressive carcinoma cells but also by the brain parenchyma itself." (PMID 26098772, 2015). "Transforming growth factor beta (TGF-β) variants 1, 2, and colony-stimulating factor 1 (CSF1) promotes proliferation and viability in microglia, and inhibitors have been designed with the intent of mediating inflammation associated with neuropathic and cancer pain." (PMID 39634607, 2024). "Targeting the CSF-1/CSF-1R signaling pathway to disrupt CSF-1R expression has demonstrated significant therapeutic potential across various cancers." (PMID 40850976, 2025). "The cancer cells-derived CSF1 then interacts with the CSF1 receptor on MSCs, facilitating macrophage recruitment and promoting metastasis." (PMID 40676710, 2025). "Recently, the promising therapeutic potential of CSF-1/CSF-1R signaling pathway inhibition in cancer treatment is widely used." (PMID 40007537, 2025). "In the second loop, TA-MSCs enhance cancer cells secretion of CSF1 by releasing CCL5, which binds to CCR5 on cancer cells." (PMID 40676710, 2025). "Clinical trials across various cancer types have explored drugs that inhibit this CSF-1/CSF1-R pathway, utilizing both monoclonal antibodies and small-molecule inhibitors." (PMID 39766202, 2024). "CSF1R is a macrophage chemokine receptor that is present in all TAMs, whereas its ligand CSF1 can be produced by cancer cells and other components of the TME." (PMID 39068459, 2024). "CAFs-derived colony-stimulating factor 1 can recruit monocyte and trans-differentiation toward the TAM2 via the interaction of colony-stimulating factor 1 and its receptor to promote cancer progression." (PMID 38644492, 2024). "Antibody‐mediated targeting of the CSF1‐CSF1R axis and depletion of macrophages through pharmacological CSF1 inhibition demonstrated reduced tumor progression and increased chemosensitivity in several mouse models of cancer." (PMID 38426622, 2024). "On the other hand, TAMs channel cancer cells into the bloodstream through a positive feedback circuit comprising CSF-1 secreted by the cancer cells and EGF secreted by TAMs." (PMID 38397421, 2024).
cancer (continued). "Another type of CSF1 therapy, cabiralizumab, has shown safety in combination with other immunotherapies in a phase 1 trial for several cancer types." (PMID 38612926, 2024). "Cancer cells recruit TAMs by secreting colony-stimulating factor-1, and in return, TAMs facilitate cancer cell growth by producing EGF." (PMID 38254110, 2024). "The upregulation of FASN in specific mouse TAM subsets due to the secretion of CSF1 by cancer cells supports in vivo lung tumorigenesis." (PMID 38302980, 2024). "This phenomenon underlines the possible reasons for the poor efficacy of a single anti-CSF1 or MIF in cancer treatment." (PMID 39323622, 2024). "Multiple studies have demonstrated that inhibiting the interaction of CSF-1/CSF-1R, leading to the elimination of TAMs, is an effective strategy in cancer therapy." (PMID 38646440, 2024). "High levels of serum CSF-1 were considered the cancer biomarkers in certain tumors, including squamous cell carcinoma of the head and neck and colorectal cancer." (PMID 38254773, 2024). "Subsequently, homing MSCs secrete CCL5, which binds to CCR5 on cancer cells, inducing the secretion of CSF1 by cancer cells." (PMID 39070181, 2024). "The macrophage growth factor Colony Stimulating Factor-1 (CSF-1) is strongly pro-tumorigenic in most cancers, as the activation of the Colony Stimulating Factor-1 Receptor (CSF-1R) promotes the M2 polarization of TAMs." (PMID 39194679, 2024). "Cancer cells secrete CSF1, thereby stimulating macrophages to produce EGF which in turn triggers the migration of cancer cells." (PMID 39003350, 2024). "CSF-1, a major growth and differentiation factor released by cancer cells, interacts with its cognate receptor, CSF-1R, which is widely expressed by macrophages and monocytes." (PMID 39403370, 2024). "The existing literature on this topic is insufficient, highlighting the need for further research to enhance our understanding of these regulatory mechanisms and the role of endothelial cells in producing CSF-1 in cancer." (PMID 39457693, 2024). "Under standard conditions, CSF-1 is released by cancer cells as a soluble ligand which acts on macrophages via the CSF-1R in a paracrine and possibly endocrine fashion." (PMID 39194679, 2024). "During tumorigenesis, cancer cells secrete colony-stimulating factor 1 (CSF-1) to recruit macrophages, which, in turn, release GDNF, promoting cancer migration as well as nerve invasion." (PMID 37610689, 2024). "Colony stimulating factor-1 (CSF-1) is produced by certain cancers and is responsible for recruiting myeloid cells that suppress antitumor immunity." (PMID 36980578, 2023). "Simultaneously, cancer cells produce colony-stimulating factor-1 (CSF-1) that strenghtens EGF expression in macrophages." (PMID 36835266, 2023). "M1-type TAMs, which are mainly activated by IFN-γ, LPS, and CSF1, present antigens and exert cytotoxic effects on cancer cells." (PMID 37233869, 2023). "Other phase I and II studies involving blockade of the CSF-1/CSF1R pathway are underway in different types of cancers." (PMID 37143666, 2023). "Currently, few studies have investigated the combination of cancer vaccines with CSF1/CSF1R inhibition." (PMID 37505292, 2023). "Next, we explored macrophage and cancer cell viability following CSF1/CSF1R pathway inhibition and CD40L/CD40 pathway activation in the MTS for 4 and 7 days." (PMID 37346794, 2023). "Senescent cancer cells also secreted colony-stimulating factor 1 (CSF1), which enhanced monocyte differentiation into M2 macrophages, with known inhibitory properties on CD8+ T cell activation." (PMID 36980201, 2023). "This cluster included genes well known to mediate CAF-TAM interactions in cancer, such as Tgfb1, Csf1, and Ccl232." (PMID 37726308, 2023). "One of the key factors is the high expression of epidermal growth factor (EGF) in TAMs, which activates epidermal growth factor receptors (EGFRs) in cancer cells, leading to metastasis and increased secretion of colony-stimulating factor 1 (CSF-1)." (PMID 37445965, 2023).
cancer (continued). "Cancer cells secrete macrophage-colony stimulating factor 1 (CSF-1), which binds to macrophages and promotes polarisation of macrophages towards an M2-like phenotype." (PMID 38143746, 2023). "TAMs and cancer cells engage in various constitutive feedback loops, in which cancer cells recruit TAMs via factors such as colony stimulating factor-1 (CSF-1, a major driver of macrophage maturation)." (PMID 37090720, 2023). "Still, our comprehensive bioinformatics analysis of cancer–nerve crosstalk-associated genes in SKCM constructed a valuable prognostic model based on eight genes (GRIN3A, CCR2, CHRNA4, CSF1, NTN1, ADRB1, CHRNB4, and CHRNG) and common clinical characteristics." (PMID 37404751, 2023). "Following analysis by ELISA, we observed that 4T1 and MC38 carcinoma cell lines produced high and intermediate amounts of CSF1, respectively." (PMID 37505292, 2023). "The CSF‐1 recruits and activates TAMs to further secrete EGF, which suggests the existence of an EGF/CSF‐1 positive feedback loop between TAMs and cancer cells." (PMID 34914196, 2022). "High epidermal growth factor (EGF) expression in TAMs activates epidermal growth factor receptors (EGFRs) in the cancer cells which in turn promotes metastasis and CSF‐1 secretion." (PMID 34914196, 2022). "On the other hand, DKK1, CTSB, CTSD, BCLX, CSF1, and CAPG are associated with the metastatic potential of cancer." (PMID 35745691, 2022). "Genomic deletion of the enhancer (via CRISPR/Cas9) enabled us to validate this regulatory element as a bona fide enhancer of CSF1 and subsequent cell-based assays revealed profound effects on cancer cell proliferation, colony formation, and migration." (PMID 35406623, 2022). "In this analysis, high-grade cancer regions with higher expression of NOS3 had elevated CSF1, CSF1R, and CD206." (PMID 36209194, 2022). "Higher circulating levels of CSF-1 are found in various pathologies including chronic inflammatory disease, cancer, and infections." (PMID 35982068, 2022). "It was previously shown that CSF-1 initiates an EGF-dependent paracrine loop between cancer cells and macrophages that supports cancer cell invasion." (PMID 35998057, 2022). "In our study we described the changes to CSF-1R expression with aging and cancer in monocytes and macrophages, however the presence of CSF-1 affects surface and intracellular expression of CSF-1R." (PMID 35821822, 2022). "Here, for the first time, we found that the enhanced survival of cancer cells achieved by TAM was mainly mediated by CXCR4 activation from the increased secretion of CXCL12 from CSF-1 activated TAM." (PMID 34069563, 2021). "In contrast, overexpression of CSF‐1 remarkably increases TAMs recruitment and accelerates cancer development and metastasis." (PMID 33463063, 2021). "The 3’UTR of colony-stimulating factor 1 (CSF-1) harbors multiple unique motifs, and CSF-1 acting as a target of various miRNAs has been documented in cancers." (PMID 34627193, 2021). "GW2580 was found to inhibit gemcitabine‐induced CSF‐1 overproduction in cancer cells and thus inhibited the recruitment of immunosuppressive myeloid cells into tumors." (PMID 33463063, 2021). "Chemotherapy-induced tissue damage promotes recruitment of MDSCs through secretion of IL-34 and CSF-1 from the cancer cells." (PMID 34209703, 2021). "Blockade of colony-stimulating factor-1 (CSF-1) or its receptor CSF-1R represents a selective approach to manipulate macrophages in cancer patients and some studies have explored this new therapeutic axis in some hematologic malignancies." (PMID 33731849, 2021). "In a mouse transplantation model based on the MCF-7 cell line, blocking CSF1 expression improved the sensitivity of cancer cells to chemotherapy drugs and reversed chemotherapy resistance." (PMID 34900411, 2021). "The tumorigenicity of CSF-1 was widely documented in various cancers, and high expression of CSF-1 predicted poor prognosis." (PMID 34627193, 2021).